PHF7 (PHD finger protein 7)
Description:
E3 ubiquitin-protein ligase which ubiquitinates histone H3 at 'Lys-14' (By similarity). Required for male fertility, via inhibition of SPOP-mediated BRDT degradation when in the presence of acetylated histone H4 in early condensing spermatids (By similarity). Stabilization of BRDT allows it to facilitate histone removal in early condensing spermatids and promote the progression of histone-to-protamine exchange (By similarity). Promotes the expression of steroidogenesis proteins in the testes, and as a result plays a role in maintaining testosterone levels and repressing osteoclastogenesis (By similarity). Promotes transcription of cardiac enhancer genes by facilitating binding of cardiac transcription factors such as MEF2C and GATA4 to target gene promoters (By similarity). Ubiquitinates histone H4. Ubiquitinates histone H2A and H3 as part of the nucleosome core particle (By similarity).
Synonyms: NYD-SP6; HSPC226; HSPC045
Tractability: Antibody: its Gene Ontology location is reachable by antibodies, with high confidence. PROTAC: ubiquitination databases record sites on it.
Gene: Protein-coding gene on chromosome 3 (52,410,507 to 52,427,966, forward strand). Ensembl gene ENSG00000010318.
Subcellular location: Nucleus
Subcellular location (Human Protein Atlas): Nuclear speckles; Nucleoplasm; Golgi apparatus
Gene Ontology:
Molecular function: protein binding; histone H3K14 ubiquitin ligase activity; ubiquitin protein ligase activity
Biological process: negative regulation of osteoclast proliferation; chromatin remodeling; protein ubiquitination
Cellular component: nuclear speck; nucleoplasm; nucleus
Genetic constraint (gnomAD): Loss-of-function variants: 11 observed, 26.68 expected, observed/expected ratio (o/e) 0.41, 90% interval 0.26 to 0.68. The upper end of that interval is the gene's LOEUF score, 0.68, which puts it in group 2 of 6, group 1 being the genes least tolerant of losing a copy. Missense variants: 227 observed, 311.03 expected, observed/expected ratio (o/e) 0.73, 90% interval 0.65 to 0.81. Synonymous variants: 110 observed, 106.73 expected, observed/expected ratio (o/e) 1.03, 90% interval 0.88 to 1.21.
Homologues: Orthologues: chimpanzee PHF7 (99% identical), macaque PHF7 (97% identical), dog PHF7 (91% identical), pig PHF7 (89% identical), rabbit PHF7 (86% identical), rat Phf7 (81% identical), guinea pig PHF7 (72% identical), mouse Phf7 (68% identical), zebrafish g2e3 (30% identical), Drosophila melanogaster Phf7 (23% identical), Drosophila melanogaster pie (21% identical), zebrafish si:ch211-57f7.7 (10% identical), and 1 more. Paralogues in human: G2E3 (31% identical), PHF11 (14% identical), PHF6 (11% identical).
Diseases named in the same sentence as PHF7 in open-access papers:
PHF7 is named in the same sentence as 13 diseases in open-access papers, as found by Europe PMC text mining. Sharing a sentence is not in itself a finding about the gene and the disease. The quoted sentences say what the papers report.
anorexia nervosa (1 paper, 2025). A disorder most often seen in adolescent females characterized by a refusal to maintain a minimally normal body weight, an intense fear of gaining weight, a disturbance in body image, and, in postmenarcheal females, the development of amenorrhea. "In addition, SMG9 in AD, TCTA in anorexia nervosa, RHOA and IMPDH2 in intelligence, CRHR1 in PD, and PHF7 in schizophrenia are all reported to be conserved among a wide range of species, although their relations with the corresponding traits remain to be explored." (PMID 39905509, 2025).
bladder squamous cell carcinoma (1 paper, 2023). A squamous cell carcinoma of the bladder arising from metaplastic epithelium. "Although there are few reports on the functions of the PHF7 and CCND2 in breast cancer, they are associated with cardiac disease, bladder squamous cell carcinoma, and neuroblastoma." (PMID 37426199, 2023).
germ cell tumor (1 paper, 2018). A benign or malignant, gonadal or extragonadal neoplasm that originates from germ cells. "Moreover, forcing PHF7 protein expression in ovarian germ cells is sufficient to disrupt female fate and give rise to a germ cell tumor." (PMID 30297796, 2018).
ovarian tumor (1 paper, 2019). "Interestingly, we also observed upregulation of three transcripts specifically annotated for the GO term ‘male sex determination’ (GO:0030238) – Phf7, chinmo and tra2, which parallels previous reports of partial germline sex transformation in sxl, ovarian tumor (otu) and bam mutants." (PMID 31649115, 2019).
tumor (2 papers, 2018 to 2024). "In this model, failure to establish silencing leads to ectopic PHF7 protein expression, which in turn drives aberrant expression of testis genes and a tumor phenotype." (PMID 30297796, 2018). "Depletion of phf7 in mutants lacking germline SXL suppresses the tumor phenotype and restores oogenesis." (PMID 30297796, 2018). "While these data indicate that phf7 is a critical target of SETDB1 silencing, our finding that the phenotype was not fully rescued suggests that ectopic expression of one or more of the other SETDB1 target genes we identified in this study also contribute to the tumor phenotype." (PMID 30297796, 2018).
cancer (1 paper, 2023). A tumor composed of atypical neoplastic, often pleomorphic cells that invade other tissues. "For ERRFI1, RTN4, PHF7, SPRY4, CCND2, and RPL19, H3K36me3 and H3K79me2 enriched higher signals in normal cell lines than that in cancer cells, and the signals of H3K79me2 changed more significantly than H3K36me3 during tumorigenesis." (PMID 37426199, 2023).
PHF7 also shares sentences with these, for which no sentence is quoted: bipolar disorder (1 paper); brain tumor (1); breast carcinoma (1); cardiac disease (1); Infertility (1); neuroblastoma (1); schizophrenia (1).